FXN (frataxin)
Diseases named in the same sentence as FXN in open-access papers (continued):
Sharing a sentence is not in itself a finding about the gene and the disease.
Friedreich ataxia (continued). "Reduced expression levels of FXN in humans are linked to the development, progression, and severity of Friedreich’s ataxia (FA), a neurodegenerative disease that is supposed to be linked to disproportion in iron concentration." (PMID 35712353, 2022). "Friedreich’s Ataxia (FRDA) is a rare progressive neurodegenerative inherited disorder caused by the low expression of frataxin, which is a small mitochondrial protein." (PMID 35769335, 2022). "Friedreich’s ataxia (FRDA) is a rare genetic disorder caused by mutations in the gene frataxin, encoding for a mitochondrial protein involved in iron handling and in the biogenesis of iron−sulphur clusters, and leading to progressive nervous system damage." (PMID 35682973, 2022). "FXN variants are at the basis of neurological impairment (the Friedreich’s ataxia) and several types of cancer." (PMID 35335316, 2022). "Of particular importance, frataxin deficiency leads to Friedreich ataxia (FRDA), the most common hereditary ataxia in humans." (PMID 35420383, 2022). "Friedreich Ataxia (FA) is a rare neuro-cardiodegenerative disease caused by mutations in the frataxin (FXN) gene." (PMID 35038030, 2022). "Friedreich ataxia (FRDA) is a life-shortening autosomal recessive neurodegenerative disorder caused by deficiency of the mitochondrial protein frataxin." (PMID 35401081, 2022). "One example includes Friedreich’s Ataxia (FRDA) caused by loss of the protein frataxin, which is a mitochondrial protein involved in energy homeostasis." (PMID 35216312, 2022). "Examples include WFS1/WFS2 mutations in Wolfram-syndrome, MANF mutations associated with a neurodevelopmental disorder, repeat insertions in FXN causing Friedreich’s ataxia and EIF2AK3 mutations in Wolcott-Rallison syndrome." (PMID 35008927, 2022). "Friedreich’s ataxia is a rare hereditary neurodegenerative disease caused by decreased levels of the mitochondrial protein frataxin." (PMID 35413853, 2022). "Friedreich’s ataxia (FRDA) is an autosomal recessive neurodegenerative disorder caused by a triplet guanine-adenine-adenine (GAA) repeat expansion in intron 1 of the FXN gene, which leads to decreased levels of the frataxin protein." (PMID 35850241, 2022). "Patients with Friedreich’s ataxia were caused by abnormal copy number of GAA trinucleotide repeat in FXN gene." (PMID 36846102, 2022). "Friedreich’s ataxia is caused by mutations on chromosome 9, in the gene coding for the frataxin protein (FXN)." (PMID 35310092, 2022). "Codon-optimized human frataxin (FXN) mRNAs were encapsulated in LNPs to treat Friedreich’s ataxia caused by the downregulation of FXN in 2016." (PMID 35335310, 2022). "GAA triplet expansions in the FXN gene cause the single most common hereditary cause of ataxia in Caucasian natives, that is Friedreich’s ataxia (FRDA)." (PMID 34817726, 2022). "One such miniSINEUP, targeting human FXN mRNA, increased frataxin protein to physiological levels and promoted the recovery of disease-associated mitochondrial aconitase defects in Friedreich’s ataxia fibroblasts." (PMID 36250017, 2022). "Friedreich’s ataxia (FA) is caused by a deficiency of the mitochondrial protein frataxin, expressed from the FXN gene." (PMID 36511872, 2022). "Friedreich’s ataxia is a rare, genetic neurodegenerative disease caused by mutations in the frataxin gene (FXN)." (PMID 36361939, 2022). "Friedreich’s ataxia (FRDA) is a degenerative disease caused by a decrease in the mitochondrial protein frataxin (Fxn), which is involved in iron–sulfur cluster (ISC) synthesis." (PMID 35472330, 2022). "Friedreich ataxia is a rare neurodegenerative disorder caused by insufficient levels of the essential mitochondrial protein frataxin." (PMID 35221903, 2022). "Much work has been undertaken on the characterization of frataxin in humans because its deficiency is the cause of the autosomal recessive disease Friedreich’s ataxia." (PMID 35893635, 2022).
Friedreich ataxia (continued). "Friedreich’s ataxia (FRDA) is an inherited disorder caused by reduced levels of frataxin (FXN), which is required for iron-sulfur cluster biogenesis." (PMID 35531957, 2022). "Friedreich’s ataxia (FRDA) is a hereditary neurodegenerative disease caused by mutations in the frataxin (FXN) gene encoding the protein frataxin, and sensorineural hearing loss is one of the clinical symptoms of this disease." (PMID 36278017, 2022). "Friedreich ataxia patient-derived fibroblasts, as well as the FXN mutated murine fibroblasts, are more sensitive to erastin than the normal control cells." (PMID 33801920, 2021). "GLP-1 analogs improve mitochondrial function in frataxin-deficient cells and induce frataxin expression in Friedreich ataxia patients’ iPSC-derived neurons and beta-like cells." (PMID 33477961, 2021). "Friedreich’s ataxia (FRDA) is an autosomal recessive disorder caused by the abnormal expansion of GAA repeats contributing to suppressed expression of frataxin (FXN) protein." (PMID 33509239, 2021). "LYRM4 deficiency results in symptoms caused by frataxin deficiency associated with Friedreich’s ataxia, leading to the conclusion that LYRM4 facilitates FXN regulation of [2Fe-2S] cluster formation." (PMID 34573089, 2021). "Friedreich ataxia (FRDA) is typically caused by homozygosity for an expanded GAA triplet-repeat in intron 1 of the FXN gene." (PMID 34899161, 2021). "Mutation in the FXN gene encoding frataxin, the protein involved in Fe–S cluster assembly, cause Friedreich's ataxia (spinocerebellar degeneration) that is also associated with Fe overload." (PMID 34732319, 2021). "Methionine BT is reported in hepatitis C-infected cells, and in patients with Friedreich ataxia an autosomal recessive degenerative disorder caused by loss of function mutations in the frataxin gene (FXN gene), located on chromosome 9q13." (PMID 34299321, 2021). "Friedreich’s Ataxia (FRDA) is the most frequent autosomal recessive inherited ataxia caused by mutations in the FXN gene." (PMID 33599954, 2021). "It has been reported that FXN, the major causative gene of Friedreich ataxia, is possibly involved in ferroptosis." (PMID 33801920, 2021). "Frataxin is a mitochondrial protein which deficiency causes Friedreich’s ataxia, a cardio-neurodegenerative disease." (PMID 33672495, 2021). "Frataxin (FXN) is a highly conserved mitochondrial protein whose deficiency causes Friedreich’s ataxia, a neurodegenerative disease." (PMID 34944579, 2021). "Formation of non-canonical structures in the first intron of the frataxin gene interfere with its transcription, drastically reducing the levels of the protein frataxin and causing the pathology associated with Friedreich’s ataxia." (PMID 32821947, 2020). "Frataxin is an important mitochondrial protein and its decrease causes Friedreich’s ataxia (FRDA), a lethal neurodegenerative disease." (PMID 32184761, 2020). "Friedreich's ataxia is an autosomal recessive neurodegenerative disease caused by decreased expression of frataxin, a mitochondrial protein, leading to mitochondrial dysfunction." (PMID 32656499, 2020). "Friedreich's ataxia is mainly caused by the insufficient production of frataxin, a mitochondrial protein." (PMID 32813850, 2020). "Patient’s with Friedreich’s Ataxia (FRDA) display an autosomal recessive mutation in the frataxin gene on chromosome nine and display symptoms such as ataxia, diabetes, limb failure, and severe cardiomyopathy." (PMID 33912028, 2020). "In this study, the neural phenotype is explored in rodent models of the spinocerebellar disorder known as the Friedreich Ataxia (FA), which results from mutations within the gene encoding the Frataxin mitochondrial protein." (PMID 32906751, 2020). "Friedreich’s ataxia (FRDA) is a progressive neurodegenerative disorder caused by a homozygous GAA repeat expansion mutation in intron 1 of the frataxin gene (FXN), which instigates reduced transcription." (PMID 32582297, 2020).
Friedreich ataxia (continued). "Friedreich ́s ataxia is mainly caused by a GAA trinucleotide repeat expansion within the first intron of the FXN gene." (PMID 32933002, 2020). "In support of this model, frataxin mutation has been shown to cause an increase in ROS production, as well as a decrease in mitochondrial membrane potential (ΔΨm) in Friedreich’s ataxia model." (PMID 32499495, 2020). "The iron-sulfur cluster (ISC) assembly complex is activated by frataxin (FXN) and Friedreich’s ataxia is caused by FXN deficiency." (PMID 31101807, 2019). "In the majority of patients Friedreich ataxia is caused by homozygous pathological expansion of GAA repeats in the first intron of the FXN gene." (PMID 33324899, 2019). "Friedreich ataxia is a human neurodegenerative and myocardial disease associated with a decreased production of the mitochondrial protein frataxin." (PMID 31319631, 2019). "In a Drosophila model of Friedreich’s ataxia, upregulation of mitoferrin associated with frataxin deficiency is observed." (PMID 30881284, 2019). "Friedreich ataxia (FRDA) is a rare neurological disorder due to deficiency of the mitochondrial protein frataxin." (PMID 31105516, 2019). "Since the discovery that Friedreich’s ataxia (FA), a severe neurodegenerative and cardiac disease that is the most common form of recessive ataxia is caused by defective expression of FXN, this protein has been the focus of intense research." (PMID 31395877, 2019). "Friedreich’s ataxia (FRDA) is a hereditary neuromuscular degenerative disease caused by a trinucleotide repeat expansion mutation in the first intron of the frataxin (FXN) gene." (PMID 31286988, 2019). "Friedreich's ataxia, however, is caused by an unusual mechanism that involves the mutant trinucleotide repeat forming an R-loop at the FXN locus." (PMID 31151992, 2019). "We optimised the technique to study the effects of frataxin overexpression in a cellular model of Friedreich’s ataxia, a neurodegenerative disease caused by partial silencing of the FXN gene." (PMID 31848436, 2019). "Deficiency in FXN leads to the loss-of-function neurodegenerative disorder Friedreich’s ataxia (FRDA)." (PMID 31101807, 2019). "Iron-sulfur (Fe-S) clusters are essential protein cofactors whose biosynthetic defects lead to severe diseases among which is Friedreich’s ataxia caused by impaired expression of frataxin (FXN)." (PMID 31395877, 2019). "Friedreich’s ataxia (FRDA) is an early-onset neurodegenerative disorder primarily caused by homozygous (GAA) repeat expansion in the first intron of the frataxin gene (FXN), located on chromosome 9q21.1." (PMID 31680804, 2019). "Friedreich’s ataxia (FRDA) is an autosomal recessive neurodegenerative disorder caused by an expanded (GAA) trinucleotide repeat in the FXN gene." (PMID 31680804, 2019). "Friedreich ataxia (FRDA) is an autosomal recessive neurodegenerative disease caused by a defect in the gene FXN which encodes for the mitochondrial protein frataxin." (PMID 31721791, 2019). "Since the description of frataxin deficiency as the cause of Friedreich’s ataxia, multiple other deficiencies in ISC biosynthesis pathway have been reported." (PMID 29623423, 2018). "Friedreich's ataxia is a neurodegenerative disorder associated with a GAA trinucleotide repeat expansion in intron 1 of the frataxin (FXN) gene." (PMID 30159187, 2018). "FXN deficiency is closely associated with increased oxidative stress damage in Friedreich ataxia (FRDA), an autosomal recessive disease characterized by progressive neurodegeneration in the spinal cord and hypertrophic cardiomyopathy." (PMID 29555919, 2018). "Friedreich ataxia is a multi-system autosomal recessive inherited disorder primarily caused by homozygous GAA repeat expansion mutations within intron 1 of the frataxin gene." (PMID 30519163, 2018). "Frataxin is a nuclear-encoded mitochondrial protein whose deficiency is the cause of Friedreich’s ataxia, a hereditary cardio- and neurodegenerative disease in humans." (PMID 30519254, 2018).
Friedreich ataxia (continued). "Friedreich's ataxia (FRDA) is a rare hereditary neurodegenerative disorder caused by a GAA repeat expansion in the FXN gene." (PMID 30237783, 2018). "Frataxin is the protein responsible for the genetically-inherited neurodegenerative disease Friedreich’s ataxia caused by partial silencing of the protein and loss of function." (PMID 29090418, 2018). "One of the proteins involved in the process is frataxin, a protein whose reduced levels cause in humans the neurodegenerative disease Friedreich’s ataxia." (PMID 29090418, 2018). "Friedreich's ataxia is a disease caused by a decrease in the levels of expression or loss of functionality of the mitochondrial protein frataxin (FXN)." (PMID 29511616, 2018). "Friedreich's ataxia (FA) is caused by reduced levels of frataxin, a highly conserved mitochondrial protein." (PMID 29898895, 2018). "The neurodegenerative disease Friedreich's ataxia is caused by lower than normal levels of frataxin, an important protein involved in iron–sulfur (Fe-S) cluster biogenesis." (PMID 29794127, 2018). "Expansion of a GAA trinucleotide repeat in the FXN gene results in cellular depletion of frataxin protein and causes the autosomal recessive neurodegenerative disease Friedreich's ataxia (FRDA)." (PMID 30031876, 2018). "Deficiency of FXN is associated with the neurodegenerative disease Friedreich ataxia, commonly resulting from a GAA trinucleotide repeat expansion in the FXN gene." (PMID 30200358, 2018). "Friedreich ataxia (FRDA) is an autosomal recessive neurodegenerative condition due to a deficiency in the mitochondrial protein frataxin (FXN), and in 96% of affected individuals it is due to homozygosity of a GAA repeat expansion in intron 1 of the FXN gene." (PMID 30596685, 2018). "GAA triplet expansions in the FXN (frataxin) gene are the most usual cause of Friedreich ataxia, a form of progressive damage of the nervous system." (PMID 30591019, 2018). "Friedreich’s ataxia (FA) is a genetic disorder caused by a GAA repeat expansion within the first intron of the frataxin gene (FXN) and is characterised by a number of clinical manifestations, including cerebellar ataxia and cardiomyopathy." (PMID 28456899, 2017). "Among these interactions, a particularly interesting one is that with CyaY, since this protein is the bacterial ortholog of frataxin which, in humans, is linked to the neurodegenerative Friedreich's ataxia (MIM 229300)." (PMID 27474202, 2017). "Four Friedreich ataxia patients who harbor a point mutation in one FXN allele were treated with EPI-743 in an open-label study (NCT01962363)." (PMID 28467362, 2017). "Regardless of the genetic abnormality, transcription inhibition causes loss-of-function of Frataxin, and consequently pathogenesis of Friedreich ataxia." (PMID 28832669, 2017). "For example, the adult brain heatmap of iPSCs with FXN mutations shows increased expression in the myelencephalon and pons, two brain regions affected in patients with Friedreich's ataxia." (PMID 29051230, 2017). "In humans, abnormally large GAA repeats in the first intron of the gene coding for FXN result in low levels of frataxin expression, and have been linked to the autosomal recessive hereditary neurodegenerative disease Friedreich’s ataxia (FRDA)." (PMID 29200434, 2017). "Friedreich ataxia is an autosomal recessive neurodegenerative disorder caused by mutations of FXN, which encodes frataxin, a mitochondrial iron-binding protein involved in the synthesis of the Fe–S clusters required by the ETC complexes." (PMID 27504452, 2016). "Friedreich's ataxia is an incurable genetic disorder caused by a mutant expansion of the trinucleotide GAA within an intronic FXN RNA." (PMID 26842135, 2016). "Friedreich’s ataxia (FA) is an autosomal recessive neurodegenerative disease caused by a guanine-adenine-adenine triplet repeat expansion in the first intron of frataxin." (PMID 27165726, 2016).
Friedreich ataxia (continued). "The aim of this study is to investigate the folding reaction of human frataxin, whose deficiency causes the neurodegenerative disease Friedreich’s Ataxia (FRDA)." (PMID 26856628, 2016). "Friedreich’s ataxia is most commonly caused by trinucleotide repeat expansion of GAA within the first intron of the nuclear encoded gene frataxin, leading to reduced expression by gene silencing." (PMID 27078885, 2016). "Friedreich’s ataxia (FRDA) is an autosomal recessive neurodegenerative disease caused by mutations in Frataxin (FXN)." (PMID 27901468, 2016). "Friedreich ataxia is a neurodegenerative disease caused by a GAA triplet repeat expansion in the first intron of the frataxin gene, which results in reduced expression levels of the corresponding protein." (PMID 27106929, 2016). "The molecular cause of the neurodegenerative disease Friedreich ataxia is the reduction of the mitochondrial protein frataxin below a critical level." (PMID 27106929, 2016). "Friedreich ataxia (FRDA) is a loss-of-function disease caused by an expanded intronic GAA repeat in the Frataxin (FXN) gene, and in our analysis it displayed the greatest number of epigenetic marks in its distance profile." (PMID 27013954, 2016). "Expansion of (GAA)n repeats in the first intron of the Frataxin gene is associated with reduced mRNA and protein levels and the development of Friedreich’s ataxia." (PMID 27846236, 2016). "Friedreich ataxia (FRDA) is a progressive neurodegenerative disease caused by deficiency of frataxin protein, with the primary sites of pathology being the large sensory neurons of the dorsal root ganglia and the cerebellum." (PMID 27518705, 2016). "Frataxin was discovered because mutations in the corresponding gene cause the neurodegenerative disease Friedreich’s ataxia." (PMID 25996596, 2015). "Frataxin deficiency is associated with the Friedreich’s ataxia (FRDA) phenotype, a cardio- and neuro-degenerative disease in humans." (PMID 26517126, 2015). "Friedreich’s Ataxia is a genetic disease caused by expansion of an intronic trinucleotide repeat in the frataxin (FXN) gene yielding diminished FXN expression and consequently disease." (PMID 26671574, 2015). "Frataxin deficiency leads to mitochondrial dysfunction and oxidative damage that are at the origin of numerous neurodegenerative diseases like Friedreich ataxia, Parkinson and AD." (PMID 26379234, 2015). "Friedreich ataxia (FRDA) is an autosomal recessive neurodegenerative disorder caused by GAA repeat expansion mutation within intron 1 of the FXN gene." (PMID 26059974, 2015). "In humans, altered levels of FXN lead to a drastic decrease in Fe-S protein activities and cause the neurodegenerative disease Friedreich’s ataxia." (PMID 25996492, 2015). "Frataxin (Yfh1 in yeast) is a conserved protein and deficiency leads to the neurodegenerative disease Friedreich’s ataxia." (PMID 25996596, 2015). "Friedreich ataxia is caused by an expanded GAA triplet-repeat sequence in intron 1 of the FXN gene that results in epigenetic silencing of the FXN promoter." (PMID 26393353, 2015). "The significance of frataxin function is central to understanding Friedreich's ataxia, a neurodegenerative disorder caused by a gradual depletion of mature frataxin in sufferers who carry mutations in both frataxin genes." (PMID 25688831, 2015). "In eukaryotes, a defect in FXN results in severe defects in Fe-S cluster biogenesis, and in humans, this is associated with Friedreich’s ataxia, a neurodegenerative disease." (PMID 25996492, 2015). "The protein was originally identified based on its connection to Friedreich’s ataxia, which is an inherited neurodegenerative and cardiodegenerative disease resulting from a deficiency of frataxin." (PMID 25996596, 2015). "Among these studies, Friedreich ataxia (FRDA) is relevant for a deficiency in the gene encoding frataxin, a mitochondrial protein implicated in iron metabolism and glutathione balance, and lower-than-normal CoQ10 levels." (PMID 25380523, 2014).